IL10 (interleukin 10)
Diseases named in the same sentence as IL10 in open-access papers (continued):
Sharing a sentence is not in itself a finding about the gene and the disease.
colitis (continued). "In conclusion, our results demonstrate that resveratrol treatment prevents the increase in MC in allergen-induced Th2 enteritis as well as in experimental IL-10−/− colitis." (PMID 35163137, 2022). "Taken together, these data demonstrate that treatment with (+)-JQ1 attenuates severity of colitis onset in Il10-/- mice two weeks post colonization." (PMID 35401533, 2022). "Thus ERS-induced mucin depletion seems to be a relevant pathogenetic mechanism of colitis in IL-10 deficient mice; our results demonstrating a significantly reduced number of goblet cells and expression of MUC-2, IL-18, WFDC2 and Xbp-1 in IL-10 deficient mice at young ages support this hypothesis." (PMID 36699599, 2022). "Our results showed that Bp7 and Bp8 intervention obviously reduced the colonic TNF-α and IL-1β levels and significantly elevated the colonic IL-10 levels, indicating that Bp7 or Bp8 effectively relieved the development of inflammation in colitis mice." (PMID 35681301, 2022). "Through studying the suppressive function of ILCregs in a mouse model of colitis, IL-10 inhibited the activation of both ILC1s and ILC3s, as previously discussed." (PMID 36275689, 2022). "GABA inhibits pro-Inflammatory cytokine such as IL-12, IFN-γ, and TNF-α production, while significantly increasing tissue levels of IL-10 in DSS-induced colitis." (PMID 35151255, 2022). "During chronic inflammation, IL-22 is induced and often protects against damaging tissues similar to IL-10, specifically exerting its effects during acute inflammation in mouse colitis models." (PMID 36142515, 2022). "Lcn-2 prevents intestinal inflammation and spontaneous colitis in IL-10 null mice by enhancing phagocytic bacterial clearance in macrophages and changing microbial composition, suggesting a protective role in colitis." (PMID 36341389, 2022). "In a mouse model 2′-FL significantly reduced the severity of colitis in interleukin-10 null mice by enhancing the integrity of the epithelial layer and shifting the gut microbiota to a more positive environment." (PMID 36615720, 2022). "Administration of GSK-J4, a histone demethylase inhibitor, resulted in the retinoic acid-mediated induction of tolerogenic DCs in the dextran sulfate sodium (DSS) colitis mouse model with concomitant production of IL-10 by CD4+ T cells." (PMID 36389662, 2022). "NK151, NK173, and NK175 alleviated iGm-induced colitis: they decreased IL-1β and IL-6 expression, while IL-10 and claudin-1 expression increased." (PMID 35631220, 2022). "The AhR-miR-212/132 axis has also been shown to promote intestinal inflammation within DSS-induced colitis mice via induction of Th17 cells and downregulation of Il-10-producing T cells." (PMID 35626744, 2022). "Follow up studies showed that obeticholic acid (OCA), a semi-synthetic bile acid used as medication and potent FXR agonist, prevented DC migration from the spleen to the colon in response to DSS-colitis with an increase in plasma IL-10 levels and IL-6 levels." (PMID 36569849, 2022). "Blocking the interaction between THBS1 and latent TGF-β or inhibiting TGF-β receptors (TGF-βR) significantly reversed the THBS1-mediated induction of IL-10-producing B cells and the therapeutic effects on colitis." (PMID 35371051, 2022). "Further increase in CD3+ T-cell counts was seen in IL-10−/−/β7−/− mice corresponding to their more severe colitis." (PMID 34433904, 2022). "TCRαβ+CD8αα+ IELs inhibit the onset of colitis evoked by primary splenic TCRαβ+CD4+CD45RBhi T cells in an IL-10 dependent manner." (PMID 34999729, 2022). "The protective effects of LB in the DSS-induced colitis model were related to the stimulation of IL-10 and the restoration of goblet cells and indicated it as an excellent candidate to prevent and treat diseases associated with inflammation." (PMID 36615489, 2022). "It was shown that this engineered strain increased the production of IL-10 in the intestinal epithelium, contributing to the effectiveness against colitis." (PMID 35082553, 2022).
colitis (continued). "Salubrinal has been shown to relief colonic inflammation in mice with deficiency in IL-10 and NADPH oxidase 1 or DSS-induced colitis." (PMID 35685885, 2022). "IL-10 is an anti-inflammatory cytokine that plays a protective role in mucosal surfaces against hyperinflammation, and the inhibition of IL-10 signaling has been found to promote the onset of colitis and irritable bowel syndrome (IBD)." (PMID 35628390, 2022). "Colitis and colitis-associated colon cancer (CAC) proceeded fast in a TNF-α–IL-10-deficient mouse model compared with an IL-10-deficient mouse model." (PMID 36140220, 2022). "CM whey increased the regulation of the IL-10 gene, which can lead to a significant reduction in the number of lumps and symptoms of colitis." (PMID 35493477, 2022). "Data indicate that microbiota-associated uncontrolled Th1 response is likely responsible for exacerbating colitis and adenocarcinoma formation in IL-10 mutant mice." (PMID 35625485, 2022). "Primarily owing to their capacity to release IL-10, regulatory MФs are responsible for the resolution of colitis and the re-establishment of intestinal homeostasis." (PMID 36189323, 2022). "Inconsistent with the results of our study, two studies showed Clostridium butyricum reduced colitis-associated CRC on AOM/DSS murine models and decreased proinflammatory cytokines TNF-α, IL-6, and COX-2, and increased anti-inflammatory cytokine IL-10." (PMID 36077084, 2022). "In TNBS-induced colitis and IL-10−/− mice, administration of ethyl pyruvate attenuated colitis and reduced HMGB1 expression." (PMID 36551259, 2022). "A previous colitis study using an IL-10 knockout mouse reported that GPR120 acts as an anti-inflammatory agent." (PMID 35885367, 2022). "Animal studies have shown that perivascular sensory neurotransmitter function of mesenteric arteries is profoundly impaired in an IL-10 knock out mouse colitis model." (PMID 35463755, 2022). "Mice lacking IL-10 and IL-10Rα are more likely to develop spontaneous colitis, suggesting that IL-10 plays an essential role in the prevention of IBD." (PMID 36437465, 2022). "In contrast to dietary- and gut microbe-derived AhR ligands that mediate intestinal homeostasis, oxazalone has been shown to induce AhR-dependent colitis following downregulation of anti-inflammatory factors (i.e., Il-10) in mouse models." (PMID 35626744, 2022). "In a follow up study, this group found that Bifidobacterium enhanced mitochondrial fitness and IL-10 activity of intestinal Treg cells to limit ICI-induced colitis." (PMID 36713364, 2022). "In an animal study, administration of F. prausnitzii to trinitrobenzene sulphonic acid-induced colitis mice reduced the severity of colitis, with increasing IL-10 secretion and decreasing TNF-α and IL-12 secretion in the colon." (PMID 35163104, 2022). "More importantly, we found that the increase in IL-10-producing B cells in the peritoneal cavity was also beneficial for preventing the recurrence of colitis." (PMID 35371051, 2022). "We further demonstrated that MSCs likely boosted IL-10-producing B cells, which mediated the improvement in colitis." (PMID 35371051, 2022). "To examine the role of Pygo2 in CD‐like colitis, we used lentivirus to specifically knock down (KD) or overexpress (OE) Pygo2 in Il‐10−/− mice and the intervention effect in MAT and intestinal mucosa was verified by RT‐qPCR." (PMID 35707871, 2022). "We administered a single-targeted CMV-siRTNF-α circuit and a multi-targeted CMV-siRT+B+I circuit to IL-10−/− mice and evaluated the therapeutic effects of self-assembled siRNAs in this spontaneous colitis model." (PMID 36171212, 2022). "During DSS-induced colitis, selenium also increased IL-10 production in CD4+ T cells, reducing colonic inflammation." (PMID 35529463, 2022). "The therapeutic effect of poly (lactic-co-glycolic acid)-microspheres (PLGA MSs)-carried oe-circGMCL1 in experimental colitis models of IL-10 knock-out mice was assessed." (PMID 36088391, 2022).
colitis (continued). "It has been demonstrated that IL-10 knockout mice develop colitis, thus demonstrating that IL-10 serves a key role in maintaining normal non-inflammatory intestinal immune-regulation." (PMID 35999253, 2022). "IL-10 is an anti-inflammatory cytokine, and in previous studies, IL10-/- mice spontaneously developed colitis, whereas upregulation of IL-10 alleviated CAC, which is consistent with our study." (PMID 36339623, 2022). "The results showed that JPQCD significantly reduced body weight loss, ameliorated disease activity index, and restored colon length in IL-10−/− mice with piroxicam-induced colitis." (PMID 35186102, 2022). "In this study, IL-10−/− mice, as a spontaneous colitis model, were used to explore the effect of ESM on colitis." (PMID 35662934, 2022). "Soluble proteins of S. mansoni increase mRNA expression of transforming growth factor-beta (TGF-β) and interleukin-10 (IL-10) while suppressing expression of interleukin-17 (IL-17) in murine TNBS-induced colitis." (PMID 36304936, 2022). "Using an IL-10 knockout mouse, it was demonstrated that the Enterobacteriaceae family was upregulated >100-folds and that individual inoculation of E. coli and Enterococcus faecalis resulted in colitis in IL-10 KO mice." (PMID 35625485, 2022). "Knockout of THBS1 expression in MSCs abolished their therapeutic effects in colitis and the induction of IL-10-producing B cells." (PMID 35371051, 2022). "It remains difficult to reconcile the therapeutic effect of α4β7-MAdCAM-1 blockade seen in patients treated with VDZ or ontamalimab (anti-MAdCAM-1) with the hastening effect of a parallel intervention on IL-10−/− colitis." (PMID 34433904, 2022). "Activated Tregs can suppress the progression of colitis effectively via production of inflammatory cytokines such as IL-10 and regulation of Th17s29." (PMID 35688918, 2022). "Bacteroides has been found to induce CD4 + T cells by enhancing anti-inflammatory IL-10 and suppressing pro-inflammatory IL-17 production through secreting polysaccharide A which is not only able to prevent but also cure experimental colitis in animals." (PMID 35151255, 2022). "More specifically, the administration of UC-MSC reduced the severity of TNBS-induced colitis in mice by increasing anti-inflammatory responses in colons of mice, such as the production of IL-10 and reduced production of inflammatory cytokines." (PMID 36263355, 2022). "Higher levels of pro-inflammatory cytokines including TNF-α, IL-1β, and IL-6 and lower levels of anti-inflammatory cytokine IL-10 were found in colitis mice when compared with the control group." (PMID 35911761, 2022). "These treatment-mediated changes, specifically the depletion of Il10-expressing ST2 Treg cells, is associated with colitis and expansion of pathogenic TC17 and TH17 T cell subsets in colonic tissue." (PMID 35508656, 2022). "Other studies advocate a potential therapeutic role of these IL-10-expressing ILCs in allergic diseases such as asthma, colitis, and pancreatic islet allograft rejection." (PMID 36275689, 2022). "The increased IL-1b and TNF serum levels and enhanced HIF-1 and IL-10 expression in colitis mice were suppressed by CYN therapy, and the treatment facilitated IL-4, CCL2, and PPARγ expression." (PMID 36278202, 2022). "In the context of bacterial infections, the first suggestions on the role of IL-10 in controlling inflammation came after several observations in IL-10-/- mice, which developed spontaneous colitis in response to their modified gut flora." (PMID 35464430, 2022). "In contrast, glucose treatment did not influence the cathepsin B activation in DSS-induced colitis model mice and IL-10−/− colitis mice." (PMID 35974017, 2022). "Despite promising preclinical results in animal models of colitis, IL-10 remains an unexplored therapeutic target in UC61–63." (PMID 36522454, 2022). "Immunofluorescence detection showed that the content of Il-10 in colitis tissues was increased after L. johnsonii treatment." (PMID 36398889, 2022).
colitis (continued). "The effects of AOS on proinflammatory cytokines were further investigated by ELISA analysis of IL-1β, IL-6, TNF-α, IFN-γ, and IL-10 levels in the serum of DSS-induced colitis mice." (PMID 35889822, 2022). "Studies have shown that the metabolite butyrate inhibited colitis by regulating the differentiation of Th1 and Th17 and promoting the production of IL-10." (PMID 35268045, 2022). "The authors showed that ghrelin down-regulated Th1 cytokine response and stimulated IL-10 production in TNBS-induced colitis." (PMID 36614012, 2022). "IL-27-producing L. lactis proved to be more effective than the administration of either IL-10-secreting L. lactis or IL-27 alone in resolving colitis in a preclinical mouse model." (PMID 35628274, 2022). "The histopathological characteristics of IL-10−/− mouse colitis are similar to those of human IBD, including lamellar and submucosal inflammatory cell infiltration, epithelial hyperplasia, crypt abscess, ulceration, and intestinal wall thickening." (PMID 35186102, 2022). "Improvement in colitis was found to be IL-10, TGF-β, and CTLA-4 dependent after administration of antagonistic IL-10 receptor, TGF-β, and CTLA-4 antibodies." (PMID 36466912, 2022). "This was evident as TCA and TCDCA level increases were accompanied by decreases in IFN-gamma and increases in IL-10 mRNA in the colons of DSS colitis mice treated with LcS as compared to untreated colitis mice." (PMID 36569849, 2022). "The low therapeutic efficacy of recombinant IL-10 indicates that a sustained and more mucosa-focused delivery is necessary for IL-10 to be effective against colitis." (PMID 35672695, 2022). "The ratio of IL-10 and IL-12 is used to evaluate the anti-inflammatory properties of microorganisms in in vitro and in vivo colitis mouse models, and a high ratio of IL-10/IL-12 represents high anti-inflammatory activity." (PMID 34899643, 2021). "In parallel, our findings showed a reduction of TNF and an increase in the anti-inflammatory cytokine IL-10 in the colonic tissues from animals with colitis, treated with FA5 or acadesine." (PMID 34199160, 2021). "Prdm1 and Maf double knock-out led to spontaneous colitis, mimicking the phenotype observed in IL-10 knockout mice." (PMID 34177953, 2021). "Similar to IBD patients, overgrowth of Enterobacteriaceae has been observed in various kinds of colitis models such as genetic ablation of IL-10, pathogen-induced inflammation, and chemically induced inflammation by DSS32." (PMID 33790314, 2021). "For example, mice containing MPs with truncated TGF-βR experience more severe DSS-induced colitis, with reduced IL-10 production and delayed goblet cell regeneration, demonstrating the role of TGF-β in promoting MP-mediated immunosuppression." (PMID 34650568, 2021). "In the Il10−/− spontaneous colitis model, A. pulmonis colonization significantly downregulated gene expression of several intestinal barrier molecules including Muc2, ZO-1, and Occludin." (PMID 34814945, 2021). "Specifically, the abundance of Proteobacteria (E. coli) increased over time in the conventionalized IL-10–/– mice, which coincided with the activation of spontaneous inflammation and the onset of colitis." (PMID 34603258, 2021). "The concentrations of proinflammatory cytokines IL-1β, IL-6, and CCL-2 in the colonic tissues of colitis mice decreased significantly, while anti-inflammatory cytokines IL-33 and IL-10 increased significantly." (PMID 34567209, 2021). "It was also demonstrated that EA had therapeutic effects on trinitrobenzene sulfonic acid (TNBS)-induced colitis, suppressing IL-18 and inducible nitric oxide synthase (iNOS), and increasing IL-10 in the colon." (PMID 34281592, 2021). "ELISA confirmed that HYJJ administration inhibited the levels of IL-2, IL-10 as well as IL-12 in the serum collected from mice undergoing experimental colitis." (PMID 34122086, 2021).
colitis (continued). "In IL-10-/- mice, as for a number of other models including Th1/Th17- or Th2-driven colitis, colitogenic T lymphocytes maintain their ability to produce enkephalins." (PMID 34299013, 2021). "One probiotic, Lactococcus lactis, has been successfully engineered to secrete bioactive IL-10, with the resulting strain observed to be protective in both the DSS and IL-10−/− models of murine colitis." (PMID 34451805, 2021). "On the other hand, DPA increased the expression of anti-inflammatory cytokine IL-10 in a dextran sulphate sodium-induced colitis model." (PMID 34822458, 2021). "Oral administration of TFA at or after modeling significantly attenuates the production of IL-6 and IL-17 in the sera and the tissue of colitis mice, and increased the Treg cell cytokines such as IL-10 and TGF-β." (PMID 35002710, 2021). "For example, abatacept is effective in patients with CTLA4 deficiency, as seen in a patient in our study, and HCT is known as a therapeutic option for treatment of XIAP, CGD, and IL-10 deficiency and associated IBD-like colitis." (PMID 34456911, 2021). "We found that treatment of both L.L-pMU45CR and L.L-pNU45CR reduced IL-6, IL-1β, and TNF-α expression, and restored IL-10 production which plays a regulatory role in colitis." (PMID 34650393, 2021). "Sympathectomy (6-OHDA) alleviated acute DSS colitis and aggravated chronic DSS colitis in wild-type mice and chronic colitis in Il-10–/– mice." (PMID 34335306, 2021). "Infection with H. diminuta reduces the severity of dinitrobenzene sulphonic acid (DNBS)-induced colitis in mice, and il-10 is important in this event." (PMID 34517928, 2021). "Abrogation of anti-inflammatory IL-10 signaling by administration of an anti-IL10 receptor antibody (aIL10R) results in Hh-driven colitis." (PMID 33516266, 2021). "Therapeutic application of GUT-108 was tested in a newly developed experimental colitis model using GF Il10−/− mice (129SvEv background) humanized with a fecal transplant from a healthy human donor." (PMID 34050144, 2021). "Il10−/−Il33−/− and Il10−/−Il33+/+ littermates developed colitis of similar severity beginning at approximately 12 weeks of age." (PMID 33953267, 2021). "Proteasome inhibition by the broad inhibitor MG132 was shown to abrogate the development of spontaneous colitis in IL10−/− mice, suggesting that proteasomes are required for initiation of colitis." (PMID 34356615, 2021). "Experimental colitis was induced by inoculating the GF Il10−/− mice with stool from the healthy donor that was previously verified to induce aggressive colitis in ex-GF Il10−/− mice." (PMID 34050144, 2021). "In contrast, in another study, it was observed that blockade of HTR7 in DSS-induced colitis or in IL-10−/− mice with the antagonist SB-269970 resulted in increased inflammation." (PMID 34502396, 2021). "Previous in vivo studies have suggested a protective role for IL-10 in preventing intestinal inflammation, with Il10rb−/− mice developing spontaneous colitis." (PMID 34220850, 2021). "In line with the observed actions of the TGF-β, it has been reported that the macrophage-derived IL-10 was also essential for the anti-inflammatory effects of MSCs therapy during DSS-induced colitis." (PMID 33807591, 2021). "When colitis in mice was induced via IL-10−/−, it was shown that the disease worsened in combination with SERT deletion, which was accompanied by increased levels of IL-6 and TNF-α mRNAs." (PMID 34502396, 2021). "A similar correlation between miR-124 and STAT3 expression levels was observed in DSS and IL-10 KO mouse models of colitis." (PMID 34571853, 2021). "Mice deficient in both IL-10 and IL-10R spontaneously develop colitis as IL-10 suppresses the inflammatory activity of various immune cells, and colitis in Il10−/− mice is mediated by Th1 cells and IFNγ." (PMID 33562334, 2021). "E. faecalis showed relatively high abundance in the intestine of IL-10-deficient mice and IBD patients and was reported to be associated with colitis induction." (PMID 34066160, 2021).